CARD9 (caspase recruitment domain family member 9)
Diseases named in the same sentence as CARD9 in open-access papers (continued):
Sharing a sentence is not in itself a finding about the gene and the disease.
fungal infections (continued). "Although dectin-1-deficient people are more susceptible to mucocutaneous fungal infection, CARD9 deficiency in human causes a more pronounced phenotype with chronic mucoctaneous as well as invasive fungal infections." (PMID 21283787, 2011). "CARD9 knockout in mice leads to mitochondrial dysfunction and apoptosis, which may explain the heightened susceptibility to intestinal inflammation and fungal infections observed in CARD9-deficient individuals." (PMID 40284630, 2025). "Notably, targeting TREM2 enhanced the antifungal immune response in vivo and in vitro, thereby alleviating the severity of CARD9-deficient subcutaneous dematiaceous fungal infection." (PMID 41329515, 2025). "Mutations in CARD9 resulting in loss of function (e.g., premature stop codon in the coding sequence) have been observed to increase susceptibility to specific fungal infections by impairing TH17 cell differentiation, leading to cytokine deficiency and making it a significant risk factor." (PMID 40725051, 2025). "In conclusion, CARD9 deficiency should be considered in the differential diagnosis of patients presenting with progressive fungal infections of unknown etiology." (PMID 40740345, 2025). "Fungal infections associated with CARD9 deficiency exhibit remarkable heterogeneity." (PMID 40740345, 2025). "Dectin-1, Dectin-2, Dectin-3, and CARD9 are key molecules responsible for host defense against fungi, and mutations in any of the genes encoding these molecules correlate with human susceptibility to fungal infections." (PMID 40284630, 2025). "Genetic deficiency in Card9 is considered an autosomal recessive primary immunodeficiency disorder (PID) which uniquely manifests as an extreme susceptibility to the development of severe fungal infection." (PMID 38921420, 2024). "Humans with mutations in CARD9 succumb to several different severe and chronic fungal infections." (PMID 38921395, 2024). "TRIM62 regulates anti‐fungal immunity in the intestine by promoting CARD9‐mediated signalling pathway, and its deficiency may increase susceptibility to fungal infections, such as those caused by Candida albicans." (PMID 35373402, 2022). "Identification of intestinal fungi through C-lectin receptors depends on CARD9 in the signaling pathway to stimulate a pro-inflammatory response to commensal fungi, and a defect in CARD9 is associated with susceptibility to fungal infections and a lower number of Th-17 cells in humans." (PMID 36237548, 2022). "In general, CARD9-deficiency patients greatly impaired the neutrophil functions, showed an inhibited secretion of inflammatory factor, and further resulted in the patients' suppressed antifungal immunity, and eventually induced fungal infection in the CNS." (PMID 33488294, 2021). "Studies utilizing an experimental model of pulmonary cryptococcosis in which mice received intratracheal inoculations with Cryptococcus serotype A, B, C, D or an AD hybrid, demonstrated that CARD9-deficient mice were susceptible to the fungal infections at an early time point." (PMID 31911495, 2020). "For instance, association between Dok-3 and Card9 is pivotal for suppressing Card9 signaling and hence restraining the fungicidal properties of neutrophils such as phagocytosis, pro-inflammatory cytokines release and NETs formation during fungal infection." (PMID 33133079, 2020). "TRIM62 or CARD9 variants are therefore potential therapeutic targets for fungal infections." (PMID 29449845, 2018). "Severe fungal infections in healthy patients have recently been reported from a few countries, i.e., Algeria, Brazil, France, China, Iran, Morocco and Tunisia and linked to autosomal recessive CARD9 deficiency." (PMID 30369919, 2018). "CARD9 deficiency should be considered in patients with unexplained progressive fungal infection, as it may allow early initiation of appropriate antifungal treatment." (PMID 30369919, 2018).
fungal infections (continued). "Because CARD9 is a central molecule to many overlapping signaling pathways, one can understand why its absence can result in high susceptibility to mucosal and systemic fungal infections." (PMID 29518906, 2018). "In addition to deleterious mutations which predispose to fungal infection, there have been reports of genetic variants of CARD9 in humans that associate with autoimmune disease." (PMID 30127791, 2018). "The first syndrome associated with CARD9 deficiency affects the skin and subcutaneous tissues, and patients in this category present with dramatic persistent fungal infections of the skin, nails and/or scalp, with occasional contiguous dissemination to the subcutaneous layers, lymph nodes and bone." (PMID 27092298, 2016). "Drewniak and others (2013) showed that human CARD9 deficiency resulted in selective defect in the host defense against invasive fungal infection caused by an impaired phagocyte killing; this suggest that CARD9-dependent CLRs other than Dectin-2 are also important for Candida killing." (PMID 27046240, 2016). "Our group's research recently uncovered novel insight into how human CARD9-deficiency may predispose to fungal infection of the CNS." (PMID 27092298, 2016). "Interestingly, Prkcd−/− mice were similar to Card9−/− mice in being highly susceptible to fungal infections." (PMID 22265677, 2012). "Research indicates that CARD9 deficiency leads to impaired cytokine secretion in both innate and adaptive immune responses, with a significant reduction in GM-CSF expression, thereby compromising host immunity and increasing susceptibility to dematiaceous fungal infections." (PMID 41190069, 2025). "The lack of homozygous mutants at the five putative missense mutations could also be viewed as evidence supporting a potential effect on CARD9 functioning, assuming deleterious mutations related to fungal infection susceptibility in koalas behave similarly to those seen in humans." (PMID 38921395, 2024). "Hence, we conjectured that fungal specificity might also contribute to the clinical phenotype in CARD9 deficient patients with dematiaceous fungal infections." (PMID 36159827, 2022). "As a key adaptor molecule in the downstream signaling of several C-type lectin receptors, CARD9 deficiency may lead to different fungal infections, including mucocutaneous or invasive candidiasis, deep dermatophytosis, phaeohyphomycosis, extrapulmonary aspergillosis, mucormycosis and trichosporosis." (PMID 36159827, 2022). "The current study reviewed 60 reported cases with CARD9 mutations and severe fungal infections, which may provide more information about the relationship between these mutations, the specific geographic presence and the unique predisposition to a particular fungal disease." (PMID 30369919, 2018). "As reported that the molecular mechanism of NF‐κB and p38 activation was associated in Card9‐Bcl10 complex in fungal infections 17, our study initially investigated whether the inducible formation of Card9‐Bcl10 complex was observed during aseptic inflammation phase of AP." (PMID 26893103, 2016). "CARD9 is a crucial adaptor protein in the innate immune response against fungal infections and its Online Mendelian Inheritance in Man (OMIM) number is 607212." (PMID 40740345, 2025). "Caspase recruitment domain containing protein 9 (CARD9) deficiency is an autosomal-recessive primary immunodeficiency disorder, undermines the body’s capacity to combat fungal infections." (PMID 40740345, 2025). "Fungal infections in the CNS result in Clec7a- and Syk-induced CARD9 activation, culminating in increased IL-1β secretion." (PMID 41386298, 2025). "Further characterization of dogs with CARD9 deficiency will offer new insight into host defense against MAC and fungal infections." (PMID 38710903, 2024). "In the case of fungal infections, CARD9 primarily regulates cytokine and chemokine production and cell migration." (PMID 38473845, 2024).
fungal infections (continued). "This response contrasts with the role of CARD9 in inducing an infectious response to fungal infections." (PMID 38473845, 2024). "CARD9 has classically been defined for its roles in driving myeloid cell inflammatory responses in the context of peripheral fungal infection." (PMID 37276426, 2023). "Emerging evidence demonstrates that CARD9 is not only present in dendritic cells and macrophages but also in neutrophils, exhibiting a similar role in fungal infection, bacterial infection, and autoimmune diseases." (PMID 33488294, 2021). "Here, the adaptor protein negatively regulates cytokine expression by fine-tuning pro-IL-1β expression in macrophages following bacterial infection, contrasting its role in fungal infection in which CARD9 primarily drives pro-inflammatory cytokine responses." (PMID 34209576, 2021). "It has been reported that a number of major SNPs are associated with susceptibility of fungal infections and diseases, including MBL2, TLR1/4/6/9, CARD9, CXCL2, DECTIN1, IL4/10/15/2, and HLA." (PMID 33362211, 2020). "The impact of CARD9 on the induction of protective immune responses against fungi has been characterized in endemic mycosis; however, the role of CARD9 during the induction of vaccine-mediated immunity to Cryptococcus has yet to be determined." (PMID 31911495, 2020). "Corticosteroids activate the glucocorticoid receptor, which is directly antagonistic to NF-κB, a central transcription factor for pro-inflammatory cytokine production that is activated by Syk-CARD9 signalling during fungal infection." (PMID 30987351, 2019). "Subsequently, research groups provided direct evidence that CARD9 signaling induced CXCL chemokine and initiated neutrophil recruitment in response to fungal infection in CARD9 knockout mice." (PMID 29352133, 2018). "As it is reported before, CARD9 is also important for recruitment of neutrophils to protect against invasive fungal infection." (PMID 30131805, 2018). "It has been well established that CARD9 positively modulates host immune responses following fungal infection." (PMID 29449845, 2018). "Our data identify a negative regulatory role for CARD9 on IL-1β production in bacterial infection that contrasts its role in fungal infections in which it drives proinflammatory responses." (PMID 27670879, 2016). "Recent studies demonstrate that Card9 expression in mononuclear cells serves as vital immune inflammation responses for defence against bacterial and fungal infection." (PMID 26893103, 2016). "Card9 is mainly located in monocyte‐macrophage cells, in which they are responsible for defence against bacterial and fungal infection, acting as a marked activation of NF‐κB and MAPKs signalling pathways for the inflammatory cascade reaction." (PMID 26893103, 2016). "In the present study, we show that the antifungal adaptor molecule CARD9 is critical for neutrophil recruitment from the blood into the CNS during fungal infection in mice and humans." (PMID 26679537, 2015). "Dectin-2 can couple to the Syk-CARD9 innate signaling pathway to activate DCs and regulate adaptive immune responses to fungal infection." (PMID 25659141, 2015). "On the one hand, severe fungal infections are associated with monogenic primary immunodeficiencies such as defects in STAT1, STAT3 or CARD9, recently discovered as novel clinical entities." (PMID 23629947, 2013). "Human CARD9 deficiency predisposes to invasive fungal infections in the absence of systemic disease, antibiotic or corticosteroid use, cancer, or trauma." (PMID 40424070, 2025). "Susceptibility to fungal infections in patients lacking CARD9 is primarily attributed to impaired production of pro-inflammatory cytokines and chemokines, compromised neutrophil recruitment, and dysregulated activation of pathways such as NF-κB and MAPK." (PMID 41041311, 2025). "CARD9 is an adaptor molecule that plays a role in myeloid cell responses to fungal infection." (PMID 41386298, 2025).
fungal infections (continued). "Furthermore, during fungal infections, such as A. fumigatus, C. albicans, E. spinifera, and M. irregularis, CARD9 plays a regulatory role in immune cell polarization and differentiation." (PMID 38473845, 2024). "It is notable that Card9 deficiency is the only reported human genetic disorder where mucosal and systemic Candida disease occur together in the absence of other non-fungal infections." (PMID 38921420, 2024). "Since Dok3 suppresses Card9 activity, disrupting the Dok3–Card9 interaction could potentially be a novel therapeutic strategy used to boost neutrophilic responses to fight fungal infection." (PMID 37513967, 2023). "Whether genetic variation in the CLR/CARD9 pathway may explain, at least partly, the increased prevalence of subcutaneous mycoses in certain subtropical regions warrants investigation." (PMID 36377664, 2022). "Therefore, CARD9 is the link between innate and adaptive immunity and has been further studied in microbial infections, especially invasive fungal infections." (PMID 35733381, 2022). "At present, it is known that patients with CARD9 gene mutation are prone to fungal infection, and the common pathogens are Candida, Aspergillus, and dermatophytes.There have been no reports of CARD9 mutation in patients with TM infection." (PMID 34234782, 2021). "In addition, genome-wide association studies have identified variants in the genes coding for molecules involved in the defense against fungal infections, such as the caspase recruitment domain 9 (CARD9)." (PMID 34682276, 2021). "Finally, Trim62-/- mice exhibited reduced cytokine production dependent on caspase recruitment domain-containing protein 9 (CARD9) signaling pathway, and increased susceptibility to fungal infection and DSS-induced colitis." (PMID 34956195, 2021). "Several cases of CARD9 mutations combined with fungal infections such as candidiasis have been reported, but there are no previous reports of CARD9 gene mutation combined with TM infection." (PMID 34234782, 2021). "Moreover, during fungal infection, CARD9 controls the induction of neutrophilic myeloid-derived suppressor cells (MDSCs), which prevent damaging hyperinflammation by counterbalancing T and NK cell responses." (PMID 30906296, 2019). "A recent review highlighted inborn errors in patients with CARD9 deficiency, demonstrating that CARD9 is solely associated with superficial and invasive fungal infections, rather than any susceptibility to bacterial or viral infections." (PMID 29518906, 2018). "Therefore, CARD9 appears to be a central regulator of neutrophil recruitment to specific organs during invasive fungal infection." (PMID 30127791, 2018). "CARD9 deficiency is the only reported human genetic disorder where mucosal and systemic Candida disease occur together in the absence of other non-fungal infections." (PMID 27092298, 2016). "Moreover, IL‐17 cytokines was present and functional in Card9 signalling pathway, which was induced and mounted by Card9 molecule activation in fungal infection." (PMID 26893103, 2016). "CARD9 upregulates IL-1β production in fungal infections, but whether there is a direct link between this protein and canonical inflammasome activity is unclear." (PMID 27670879, 2016). "Instead, we found that CARD9 deficiency confers a lack of CXC-chemokine induction in the CNS during fungal infection, in both mice and humans." (PMID 27092298, 2016). "Therefore, our data indicate that CARD9 is required for proper production of these chemoattractants in response to CNS fungal infection." (PMID 26679537, 2015). "Our study is the first to uncover the crucial role of CARD9 on neutrophil accumulation in the CNS during systemic fungal infection in mice and humans, and provides novel insight into the mechanisms of spontaneous susceptibility to CNS fungal infection seen in autosomal recessive CARD9 deficiency." (PMID 26679537, 2015).
fungal infections (continued). "As a polymorphism in the gene encoding the CLR DECTIN-1 (CLEC7A) has previously been shown to be associated with an increased susceptibility to fungal infections, a first set of comparisons assessed the prevalence of CLEC7A and CARD9 polymorphisms in control individuals and patients with RVVC." (PMID 25295030, 2014). "During fungal infection, the C-type lectin receptor Dectin-1, expressed on the dendritic cell, macrophage, and neutrophil surfaces, recognizes the β-glucan ligand present on the yeast cell wall and initiates the activation of Card9, a critical adaptor protein involved in antifungal defense." (PMID 37513967, 2023). "Furthermore, while excessive NF-κB signals triggered by Th17 cytokines appears to contribute to psoriatic changes, underactivity of this pathway may explain predilection to cutaneous yeast and fungal infections, as observed with hypomorphic defects in CARD9." (PMID 36733767, 2022). "CARD9-deficiency resulted in fungal infections without any immune suppression." (PMID 34975870, 2021). "In addition, Ly-GDI associates with CARD9, a caspase-recruitment domain (CARD)-containing protein, in phagosomes after bacterial and fungal infection, and binding of CARD9 suppressed LyGDI-mediated inhibition of the GTPase Rac1, thereby leading to bacterial killing in macrophages." (PMID 26469087, 2015). "Caspase recruitment domain family member 9 (CARD9) is an adaptor molecule connecting dectin-1 fungal sensing to nuclear factor κB (NF-κB) signaling and thus important in host defense against fungal infections." (PMID 30429846, 2018). "These two PIDs underscore two crucial mechanisms to control severe invasive fungal infection, namely the NADPH oxidase complex and CARD9-dependent signaling." (PMID 26845151, 2016). "To investigate CIN’s immunomodulatory mechanism, we analyzed Dectin-1 signaling components (Dectin-1, SYK, and CARD9), NF-κB activation, and proinflammatory cytokines (TNF-α and IL-1β) in RAW264.7 and PMA-differentiated THP-1 macrophages during a 24-h fungal infection." (PMID 41031111, 2025). "CARD9 is another important component of innate microbial sensing pathways identified by exome sequencing for its involvement in IBD, which also lead to the activation of the NF‐κB signalling pathway and cytokine production, especially in fungal infection." (PMID 35373402, 2022). "Furthermore, we also showed that this defect was specific to fungal infection, as neutrophil recruitment was also unaffected following bacterial brain infection, in agreement to the lack of susceptibility to bacterial meningoencephalitis in CARD9-deficient patients." (PMID 27092298, 2016). "However, this patient did not carry any variants in CARD9, IL17RA, L17RC, IL17F, STAT1, DOCK8, MALT1, or TRAF3IP2 genes that can explain the susceptibility to a severe and invasive fungal infection." (PMID 35091979, 2022).